SCRIB (scribble planar cell polarity protein)
Diseases named in the same sentence as SCRIB in open-access papers (continued):
Sharing a sentence is not in itself a finding about the gene and the disease.
cancer (continued). "Scribble acts as a tumour suppressor: Drosophila Scrib null mutants exhibit disorganization of epithelial tissues, leading to neoplastic growth and multilayering of epithelial cells and SCRIB expression is decreased in a number of human cancers." (PMID 23195221, 2013). "SCRIB was reported to be mislocalized or down-regulated in various cancers." (PMID 39796103, 2024). "However, further study is needed to clarify the significance of the expressions of FAM83H and SCRIB in predicting the prognosis of human cancers." (PMID 35885485, 2022). "However, an increasing number of reports have presented SCRIB as an important therapeutic target for cancers." (PMID 35885485, 2022). "The prognostic significance of the nuclear expressions of FAM83H and SCRIB might be related to their roles in cancer progression in conjunction with nuclear proteins important in cancer progression, such as MYC and β-catenin." (PMID 35885485, 2022). "More interestingly, in those samples where SCRIB was still detectable, it was localized solely in the cytoplasm of cancer cells, suggesting that relocation of SCRIB from cell–cell contacts may contribute to cell transformation in these tumors." (PMID 34503271, 2021). "Based on the association between SCRIB and the Wnt/β-catenin pathway, recent reports have shown the molecular relationship between MYC, FAM83H, SCRIB, and the Wnt/β-catenin pathway in human cancers." (PMID 33803371, 2021). "Therefore, our results suggest that SCRIB is involved in cancer progression and chemoresistance by activating some EMT characteristics." (PMID 33803371, 2021). "However, in contrast, recent reports have shown that the role of SCRIB in human cancer is closely related to its subcellular localization instead of its expression level." (PMID 33803371, 2021). "When considering the significant role of EMT in cancer development and progression, SCRIB might have a role in cancer progression by regulating EMT." (PMID 33803371, 2021). "SCRIB is a core member of the basolateral polarity complex, which functions in establishment of epithelial cell polarity, and it is mis‐localized or down‐regulated in many cancers." (PMID 32281270, 2020). "In this manner, FAM83H- and SCRIB-mediated stabilization of β-catenin might activate cancer progression by regulating EMT." (PMID 32564009, 2020). "Further analysis of WES data revealed additional variants in common cancer‐related genes involved in DNA replication and DNA damage (e.g., ATM, CDKN1A), cell polarization (SCRIB), proliferation (RNASEL), VEGF expression (MAP3K1, MAP3K6), and in genes encoding growth factors (FGF2) (Table EV2)." (PMID 32667137, 2020). "SCRIB is a polarity regulator known to be abnormally expressed in cancer at the protein level." (PMID 27428426, 2016). "SCRIB is a component of the apical–basal cell polarity machinery; thus, it may serve as a communication hub for polarity and as a coordinator of motility on both planes in cancer cells." (PMID 36675340, 2023). "However, further study, especially on the precise mechanism regarding the role of FAM83H-SCRIB in conventional anti-cancer therapies, is needed to select a population of patients who could potentially benefit from anti-FAM83H/SCRIB-targeted therapy." (PMID 35885485, 2022). "Therefore, the FAM83H-SCRIB pathway might be a therapeutic target for human cancers, especially for the poorly prognostic subgroup highly expressing FAM83H and SCRIB." (PMID 35885485, 2022). "Therefore, the effect of SCRIB in tumorigenesis might differ according to its subcellular localization and the molecules acting cooperatively with SCRIB in a specific type of cancer." (PMID 33803371, 2021). "Therefore, further study is needed to clarify the role of SCRIB in human cancer." (PMID 33803371, 2021). "However, the expression of SCRIB was observed in the cytoplasm and/or nuclei of human cancer cells." (PMID 33803371, 2021).
cancer (continued). "Therefore, cytoplasmic and nuclear localization of FAM83H and SCRIB might be important in cancer progression via a regulation of EMT that accompanies disruption of cellular adhesion." (PMID 32564009, 2020). "Therefore, the prognostic impact of the expression of FAM83H and SCRIB might differ according to cancer type." (PMID 32564009, 2020). "In support of our proteogenomic data mining, the publicly available Ribo-Seq-based translatomic data also implied the translational initiation and elongation of ribosomes at uSCRIB, oSCRIB, and SCRIB in human cancer cell lines." (PMID 34535749, 2021). "However, recent reports have raised the possibility that SCRIB might have a role in human cancers." (PMID 33803371, 2021). "Therefore, there might be another role of FAM83H that is unrelated to SCRIB in cancer progression." (PMID 32564009, 2020). "miR-296-5p has been shown to suppress cancer progression, metastasis, and neo-vascularization by targeting the expression of multiple genes including HMGA1, PUMA and SCRIB." (PMID 29221158, 2017). "Our findings indicate that KANK1 localization at the cell-cell junction of LECs from multilayered carcinomas leads to NOS1AP binding, disassembly of the SCRIB/NOS1AP complex, which profoundly compromises SCRIB’s ability to activate the Hippo pathway and stabilizes TAZ." (PMID 39613731, 2024). "Therefore, our results suggest that careful evaluation of the subcellular localization of FAM83H and SCRIB is important for the FAM83H and SCRIB immunostaining of cancer tissue." (PMID 35885485, 2022). "However, interestingly, SCRIB expression appears to be downregulated in HPV-positive and in poorly differentiated HPV-negative cancers graded 3/3, suggesting its potential as a biomarker." (PMID 34503271, 2021). "In the analysis of expression of FAM83H and SCRIB in human gastric tissue samples, their expression levels were significantly higher in cancer tissue compared with both non-neoplastic and precancerous lesions." (PMID 32564009, 2020). "The totality of these data supports the notion that a coordinated deregulation of SCRIB, VANGL2 and NOS1AP at the gene dosage or transcription level, possibly in conjunction with other PCP protein abnormalities, may affect cancer cell behavior in a sub-type-specific manner." (PMID 36675340, 2023). "Interestingly, the VANGL/SCRIB/NOS1AP complex only assembles in cancer cells, while normal mammary epithelia show no co-localization of NOS1AP with either VANGL or SCRIB." (PMID 36675340, 2023). "The subcellular localization of SCRIB was different between non-neoplastic cells and cancer cells." (PMID 33803371, 2021). "Therefore, further study is necessary to explore the exact mechanism of how FAM83H is involved in cancer progression in conjunction with SCRIB or independent of SCRIB." (PMID 32564009, 2020).
infection (3 papers, 2011 to 2023). The state of being infected such as from the introduction of a foreign agent such as serum, vaccine, antigenic substance or organism. "Other biologically relevant Wnt5a-dependent processes, for example, cell-specific responses to infection or SCRIB-dependent processes – including ones directing apical-basal polarity – may be impacted by the OTULIN-SCRIB interaction and Met1-Ub homeostasis." (PMID 37589075, 2023). "Therefore, it would be important to better understand the signalling pathways, such as those of cell growth and apoptosis, that are regulated by MAGI1 and SCRIB and that are disrupted upon infection with oncoviruses such as HPV." (PMID 22069443, 2011). "These new interactions can provide interesting starting points for exploration of potential new in vivo functions of MAGI1 and SCRIB that might be perturbed upon infection with HPV." (PMID 22069443, 2011).
neurodevelopmental disorder (2 papers, 2022 to 2023). A behavioral and cognitive disorder with onset during the developmental period that involves impaired or aberrant development of intellectual, motor, or social functions. "Since AnkG maintains SCRIB at the AIS, we speculate that loss of SCRIB function might be a core molecular pathology of AnkG-related neurodevelopmental disorders." (PMID 38081810, 2023). "Accumulating evidence suggests a role of SCRIB, together with other polarity genes, in neurodevelopmental disorders." (PMID 35626639, 2022).
prostate (1 paper, 2018). "E-cadherin knockout leads to a dis-assembly of the SCRIB polarity complex and the LGN/NUMA complex, causing a subsequent randomization of the luminal cell division plane and forming of multilayered, disorganized epithelia, a common feature of the early stage of prostate tumorigenesis." (PMID 30118484, 2018).
SCRIB also shares sentences with these, for which no sentence is quoted: Anxiety (2 papers); cervical neoplasm (2); bacterial infection (1); breast tumors (1); cardiovascular diseases (1); cervical intraepithelial neoplasm (1); clear cell renal cell carcinoma (1); colon cancer (1); endometrial adenocarcinoma (1); endometriosis (1); epilepsy (1); melanoma (1); neural tube defect (1); Neurological Disease (1); osteosarcoma (1); psychiatric disorder (1); retinal degeneration (1); squamous intraepithelial lesions (1); triple-negative breast carcinoma (1); virus infection (1).